MIR3917 (microRNA 3917)
Synonyms: hsa-mir-3917; mir-3917
Gene: MicroRNA gene on chromosome 1 (25,906,362 to 25,906,454, reverse strand). Ensembl gene ENSG00000283938.
Homologues: Orthologues: chimpanzee MIR3917 (100% identical).